CTLA4 (cytotoxic T-lymphocyte associated protein 4)
Diseases named in the same sentence as CTLA4 in open-access papers (continued):
Sharing a sentence is not in itself a finding about the gene and the disease.
cancer (continued). "Immune checkpoint inhibitors (ICIs) targeting programmed death‐1 (PD‐1), its ligand (PD‐L1), and cytotoxic T‐lymphocyte‐associated antigen 4 (CTLA4) have revolutionized cancer treatment by recovering the attack of T lymphocytes on the malignant cells." (PMID 31849171, 2020). "PD-1 and CTLA-4 expression on NK cells is upregulated in several types of cancer and is associated with reduced cytotoxicity and cytokine secretion." (PMID 33679726, 2020). "Recently, immune checkpoint inhibitors (ICIs), such as anti-PD-1 (Programmed cell Death 1) and anti-CTLA 4 (cytotoxic T-lymphocyte-associated protein 4), have emerged as new targets for cancer treatment, and many clinical studies have been conducted." (PMID 33096708, 2020). "Primarily, CTlA-4 and PD-1 checkpoints, just like T cells, have been implicated in NK cell dysfunction in various cancers." (PMID 32117298, 2020). "Ipilimumab is a human monoclonal IgG1 antibody against CTLA-4, allowing the body to overcome immune cancer suppression and also in cancers associated with HPV." (PMID 33050484, 2020). "The anti-cytotoxic T lymphocyte-associated antigen-4 (CTLA-4) antibody is the first ICPI which has shown remarkable benefits in the clinical treatment of cancers." (PMID 32183814, 2020). "Programmed death‐1 receptor (PD‐1) ligand (PD‐L1) and CTL‐associated antigen 4 (CTLA‐4) are checkpoint receptors that can be targeted to re-activate anticancer CD8+ T-cell responses in cancer-immune therapy." (PMID 33184433, 2020). "Early studies have shown that a high immune cytolytic activity (CYT) is significantly associated with significant pan-cancer survival benefits and effectively corresponds to anti-CTLA-4 and anti-PD-L1 immunotherapy." (PMID 32754579, 2020). "For instance, MAPK signaling has been shown to suppress the expression of negative immune checkpoints such as programmed death-ligand 1 (PD-L1) and cytotoxic T-lymphocyte-associated protein 4 (CTLA-4) in several cancers." (PMID 31936067, 2020). "In particular, new ITs primarily aim to inhibit cytotoxic T-lymphocyte-associated protein 4 (CTLA-4), programmed cell death protein 1 (PD-1), and programmed death ligand 1 (PD-L1) to enable T lymphocytes to attack cancer cells." (PMID 32878065, 2020). "Cytotoxic T-lymphocyte associated protein 4 (CTLA4) inhibitors have been shown to significantly prolong the overall survival (OS) in a wide range of cancers." (PMID 33117084, 2020). "Targeting cytotoxic T-lymphocyte-associated antigen 4 (CTLA-4), programmed cell death protein 1 (PD-1), and its ligand (PD-L1) has revolutionized cancer treatment." (PMID 33412751, 2020). "Immune checkpoints that have been targeted in cancer treatment include cytotoxic T lymphocyte-associated antigen 4 (CTLA-4) and programmed death-1 (PD-1)." (PMID 32630247, 2020). "Several meta-analyses evidenced this result in cancer-randomized clinical trials treated with ICIs, initially suggesting a more evident benefit associated with the anti-CTLA4 treatment for males vs. females." (PMID 32645881, 2020). "We further explored the predictive value of TERT mutation on the efficacy of anti‐CTLA4 treatment in certain cancer types." (PMID 32810393, 2020). "Immunotherapies blocking immune inhibitory receptors programmed cell death-1 (PD-1) and cytotoxic T-lymphocyte-associated protein-4 (CTLA-4) on T-cells have dramatically improved patient outcomes in a range of advanced cancers." (PMID 32992658, 2020). "In the next paragraphs the reported relationships between genetic variants of the CTLA-4 gene and particular cancers were described." (PMID 33519815, 2020). "Cancer immunotherapies that target the immunosuppressive checkpoint receptors cytotoxic T-lymphocyte-associated protein 4 (CTLA-4) or programmed death 1 (PD-1) and its ligand, programmed death 1 ligand (PD-L1), have changed the landscape of cancer treatment." (PMID 33239030, 2020).
cancer (continued). "Immune checkpoint inhibitors (ICIs) targeting cytotoxic T lymphocyte-associated protein 4 (CTLA-4); programmed cell death 1 (PD-1); and PD-1’s main ligand PD-L1, have been introduced for the treatment of more than a dozen types of cancers." (PMID 33086754, 2020). "Remarkable antitumoral activity has been achieved in various cancer types by blocking the inhibitory T-cell receptor cytotoxic T-lymphocyte-associated protein 4 (CTLA-4) or the programmed cell death protein 1 (PD-1/PD-L1) axis." (PMID 33182610, 2020). "Although PD-1 and CTLA4 overexpression, mutations, and gene amplification have been reported in certain cancers, the studies had small sample sizes and used different experimental approaches, making it difficult to compare the findings." (PMID 33072070, 2020). "During the 1990s, the immune checkpoint key proteins, cytotoxic T lymphocyte-associated protein 4 (CTLA-4), programmed cell death protein (PD-1), and programmed death-ligand 1 (PD-L1), revolutionized cancer therapy." (PMID 32850635, 2020). "ICBT, such as anti-programmed cell death protein 1 (anti-PD-1)/anti-programmed death-ligand 1 (anti-PD-L1) and anti-cytotoxic T-lymphocyte-associated protein 4 (anti-CTLA-4) now represent a new class of cancer therapeutics." (PMID 32380703, 2020). "In 2018, one half of the Nobel Prize in Physiology or Medicine was awarded to James Allison, who conceptualized cancer immunotherapy by targeting the immunosuppressive signal mediated by Cytotoxic T Lymphocyte-Associated Protein 4 (CTLA-4)." (PMID 32245497, 2020). "Gene set enrichment analysis of 33 cancer types provided further evidence for associations between PD-1/CTLA4 levels and cancer development and immunocyte infiltration." (PMID 33072070, 2020). "In both murine models and cancer patients, anti‐CTLA‐4 monotherapy is associated with an expansion of ICOS+ CD4+ Th1 effectors." (PMID 32508018, 2020). "Previous studies have suggested a link between CTLA-4 +49A/G polymorphism and several types of cancer risk, including hepatocellular carcinoma, colorectal cancer, and osteosarcoma." (PMID 33335608, 2020). "Successful targeting of immune checkpoints including cytotoxic T lymphocyte-associated protein 4 (CTLA-4) and programmed cell death protein 1 (PD-1) has achieved durable regressions in a wide range of human cancers (referred to as checkpoint blockade)." (PMID 32117226, 2020). "The most important finding found in literature for our research is the homozygous deletion of the defensin genes in human cancers, which is associated with Ipilimumab (anti-CTLA-4 immunotherapy) resistance." (PMID 32252405, 2020). "Forexample, antibodies engineered with high specificity against checkpoint inhibitorypathways of the T-cell protein, PD1, and cytotoxic T-lymphocyte associated protein-4(CTLA4) have led to revolutionary progress in cancer immunotherapy." (PMID 32161833, 2020). "The most important finding according to literature is the homozygous deletion of the defensin genes in human cancers, which is associated with Ipilimumab (anti-CTLA-4 immunotherapy) resistance." (PMID 32252405, 2020). "Another immune checkpoint is mediated by binding of the ligands B7-1/2 (CD80, CD86) on activated antigen-presenting cells or cancer cells to cytotoxic T-lymphocyte-associated protein 4 (CTLA-4) on T cells, which also suppresses T-cell activity." (PMID 32455628, 2020). "For example, type 1 diabetes was related to both the CD28 gene and the CTLA-4 gene, as well as rheumatoid arthritis and cancer risk in Asians." (PMID 32210155, 2020). "Cancer-specific mutations have been demonstrated to be viable targets for tumor-infiltrating lymphocytes (TILs) enabled by checkpoint inhibitors that block CTLA4 or PD1/PDL1 or by vaccine-induced immune responses." (PMID 31798635, 2019).
cancer (continued). "Cancer immunotherapy targeting anti-PD-1 (e.g., nivolumab, pembrolizumab), as well as anti-cytotoxic T-lymphocyte-associated antigen 4 (anti-CTLA-4, ipilimumab), has changed the treatment landscape of several tumors." (PMID 31440238, 2019). "ICB-based cancer immunotherapies, notably the T cell immune checkpoint inhibitors anti-cytotoxic T lymphocyte associated protein 4 (CTLA-4) and the anti-programmed cell death protein 1 (PD-1), have provided durable clinical benefit in diverse cancer patients." (PMID 31540045, 2019). "Recent advances in cancer treatment are emerging from new therapies that target T-cell inhibitory receptors, such as cytotoxic T-lymphocyte-associated antigen-4 (CTLA-4) and programmed cell death-1 (PD-1)." (PMID 31333652, 2019). "For instance, cytotoxic T-lymphocyte-associated antigen 4 (CTLA-4), programmed death 1 (PD-1), and programmed death-ligand 1 (PD-L1) have achieved satisfactory therapeutic results in different cancer treatments." (PMID 31998637, 2019). "For the past decades, immunotherapy by targeting programmed cell death-1 (PD-1), programmed cell death-ligand 1 (PD-L1), or cytotoxic T lymphocyte associated antigen 4 (CTLA-4) has revolutionized the treatment of cancer." (PMID 31801636, 2019). "Cancer cells harness immune checkpoints such as cytotoxic T-lymphocyte-associated protein 4 (CTLA-4), programmed cell death protein 1 (PD-1) and indoleamine 2,3-dioxygenase 1 (IDO1) to evade immune control." (PMID 31112568, 2019). "CAR-T cell therapy represents a landmark in the field of cancer immunotherapy along with immune checkpoint inhibitors, including programmed death-1 (PD-1) and cytotoxic T lymphocyte-associated protein-4 (CTLA-4) blockade." (PMID 31783889, 2019). "We were able to show that CTLA-4 expression is an independent marker for high risk of early cancer specific death after local therapy, but evidence for efficiency of CTLA-4 targeting therapy in an adjuvant setting is still missing." (PMID 31137694, 2019). "Recent discovery of immunosuppressive checkpoints, such as CTLA-4 (cytotoxic T-lymphocyte-associated protein 4) and PD-1, provides a very successful regimen to cancer immunotherapy, which has been awarded Nobel Prize in 2018." (PMID 31507611, 2019). "Exhausted T cells in chronic infections and cancer show expression of the surface molecule, CTLA-4 (cytotoxic T-lymphocyte-associated protein 4)." (PMID 31164886, 2019). "The FDA has approved monoclonal antibodies (mAb) for the treatment of cancer that block the immune checkpoints cytotoxic T-lymphocyte-associated protein 4 (CTLA-4) and the programmed cell death protein 1 (PD-1), or one of its two natural ligands, PD-L1." (PMID 30682108, 2019). "Blockade of immune checkpoints, including the cytotoxic T lymphocyte-associated protein (CTLA)-4 and the programmed cell death-1 (PD-1)/PD ligand-1 (PD-L1) pathway, have increased overall survival and progression-free survival of cancer patients." (PMID 31085177, 2019). "The therapeutic mechanisms of inhibitors mostly rely on blocking either the cytotoxic T-lymphocyte associated antigen-4 (CTLA-4) or programmed cell death protein-1 (PD-1) pathways, while activating the host's immune system against cancer." (PMID 32039239, 2019). "Next, we applied our approach to peripheral blood TCR beta repertoire samples from 2 cytotoxic T-lymphocyte-associated protein 4 (CTLA4) checkpoint blockade cancer immunotherapy studies." (PMID 31194732, 2019). "Taken together, our data presented herein demonstrate that antibody-triggered lysosomal degradation of CTLA-4 not only causes toxicity, but also restrains anti-cancer immunity." (PMID 31267017, 2019). "Immune checkpoint inhibitors block negative co-stimulatory signals such as programmed cell death-1 and cytotoxic T-lymphocyte-associated protein 4, ultimately reactivating anti-cancer immunity." (PMID 31521196, 2019).
cancer (continued). "Carcinoma-associated pancreatic fibroblasts promoted the expression of CTLA-4 and PD-1 in proliferating T cells, which contribute to immune evasion by inducing the expression of immune checkpoint inhibitors on CD4+ and CD8+ T cells in PDAC." (PMID 31464648, 2019). "Immune checkpoint antibodies against cytotoxic-T-lymphocyte-associated protein 4 (CTLA-4) or programmed cell death protein 1 (PD-1) have been demonstrated to be effective therapeutic approaches in a variety of cancers." (PMID 30208943, 2018). "Anti-CTLA-4 monoclonal antibodies (mAbs) confer a cancer immunotherapeutic effect (CITE) but cause severe immunotherapy-related adverse events (irAE)." (PMID 29463898, 2018). "Nowadays, immune checkpoint inhibitors have achieved notable success in a variety of cancers, which potentiate lymphocyte responses by specifically effecting on cytotoxic T lymphocyte-associated antigen 4 (CTLA-4) or programmed cell death protein 1 (PD-1)." (PMID 29589142, 2018). "Recent advances in cancer treatment have emerged from new immunotherapies targeting T-cell inhibitory receptors, including cytotoxic T-lymphocyte associated antigen (CTLA)-4 and programmed cell death (PD)-1." (PMID 29403496, 2018). "The immune system can be harnessed to detect and destroy cancer cells through inhibition of immune checkpoints, such as cytotoxic T-lymphocyte associated protein 4 (CTLA-4) and programmed cell death 1 or its ligand (PD-1 and PD-L1)." (PMID 29721177, 2018). "In recent years, immunotherapies targeting the T-cell immune checkpoint receptor PD-1, or its ligand PD-L1 and cytotoxic T lymphocyte-associated protein 4 (CTLA-4), have led to significant improvements in some cancer prognosis." (PMID 29515799, 2018). "We documented 17 malignancies, which amounts to a cancer prevalence of 12.9% in affected CTLA4 mutation carriers." (PMID 30250467, 2018). "In this regard, CTLA-4 was associated with good clinical outcome and longer survival due to its direct antiproliferative and proapoptotic effects in cancers." (PMID 28211499, 2017). "Targeting the cytotoxic T lymphocyte- associated protein-4 (CTLA-4), programed cell death protein-1 (PD-1) or programed death ligand-1 (PD-L1) by inhibitory antibodies is approved for various cancer types including NSCLC and RCC." (PMID 29088109, 2017). "The development of antibody blockade of immune checkpoint regulators such as cytotoxic T-lymphocyte-associated protein 4 (CTLA-4) and the program death-1 and its ligand (PD-1/PD-L1) axis has revolutionized cancer immunotherapy." (PMID 28977985, 2017). "CTLA-4 (Cytotoxic T-lymphocyte-associated protein 4) was the first immune checkpoint receptor clinically targeted for use in cancer treatment." (PMID 28344807, 2017). "Among these approaches, checkpoint inhibitors [PD-1 and cytotoxic T-lymphocyte-associated protein 4 (CTLA-4) antibodies] have been successfully used to treat several types of cancers." (PMID 28695111, 2017). "Checkpoint inhibitors such as antibodies against cytotoxic T-lymphocyte-associated protein 4 (anti-CTLA4) and programmed cell death 1 (anti-PD-1), etc, have been shown to be partially effective against several malignant tumors including HCC." (PMID 28881713, 2017). "Recently, immunotherapy targeting immunosuppressive proteins such as cytotoxic T-lymphocyte associated protein 4 (CTLA-4) and programmed cell death 1 (PD-1) has provided more treatment options for cancer patients." (PMID 28081243, 2017). "Majority of the studies have reported the expression of either CTLA-4 or PD-1 on immune cells in cancer; however, limited studies described the possible associations between ICR pathways in cancer." (PMID 28603527, 2017). "Several investigations have suggested that particular CTLA-4 gene polymorphisms are linked to cancer development or progression." (PMID 28097051, 2017).
cancer (continued). "Cytotoxic T-lymphocyte associated protein 4 (CTLA-4) is an essential negative regulator of T cell responses, resulting in T cell exhaustion and hence a state of T cell dysfunction in many types of cancer." (PMID 28416753, 2017). "Novel immunotherapies, or checkpoint inhibitors, targeting programmed cell death protein-1 (PD-1) and cytotoxic T lymphocyte-associated antigen-4 (CTLA-4) have significantly improved outcomes for patients with numerous different cancer types." (PMID 27595932, 2016). "There are currently several ongoing investigations but the most promising results for cancer therapy have been obtained by targeting the Cytotoxic T-lymphocyte-associated protein 4 (CTLA-4) and Programmed T cell death 1 (PD-1) receptors." (PMID 27399780, 2016). "Currently, the most relevant immune checkpoints in the field of cancer immunotherapy are Cytotoxic T-Lymphocyte Associated protein 4 (CTLA-4) and Programmed cell Death protein 1 (PD1), which are expressed on the surface of T lymphocytes." (PMID 27783034, 2016). "Two immune checkpoint proteins have garnered particular attention for their roles in cancer: cytotoxic T-lymphocyte-associated protein 4 (CTLA-4) and programmed cell death protein 1 (PD-1)." (PMID 26751469, 2016). "In settings of chronic antigen exposure, such as cancer, expression of checkpoint receptors such as PD-1, CTLA4, TIM-3, LAG-3, and 2B4 have been associated with dysfunctional T cells, often termed exhausted or tolerized." (PMID 25614821, 2015). "Our study was designed to investigate the associations between five CTLA4 SNPs (rs733618 C/T, rs4553808 A/G, rs5742909 C/T, rs231775 A/G, and rs3087243 G/A) and de novo malignancy in Chinese renal transplantation recipients." (PMID 25667935, 2015). "The two checkpoint targets that have been studied more extensively in cancer are the cytotoxic T-lymphocyte-associated antigen 4 (CTLA-4) and the programmed death 1 (PD-1) receptor." (PMID 26510455, 2015). "Recently, some studies discover that single nucleotide polymorphisms (SNPs) of the CTLA4 gene have been implicated in susceptibility to different cancer in different ethnic populations." (PMID 25667935, 2015). "The CTLA4 SNPs have been implicated in susceptibility to various cancers in different ethnic populations." (PMID 25667935, 2015). "The distinct mechanisms underlying PD-1 and CTLA-4 blockade have already been shown to synergize in the treatment of many murine and human cancers." (PMID 25763356, 2015). "While some serious auto-immune toxicities have been reported, particularly in patients being treated with anti-CTLA-4 antibodies, in most cases the risk of autoimmune complications have been outweighed by the need to treat advanced cancers." (PMID 25503774, 2014). "There was null association of CTLA-4 -1722T/C polymorphism with overall cancer risk in all genetic models." (PMID 24710335, 2014). "Phase I/II trials have identified the safety and tolerability of CTLA-4 inhibition in several cancers that include the significant risk of colitis and, hepatotoxicity, skin rash, and hypophysitis/hypopituitarism." (PMID 25374843, 2014). "The association between cytotoxic T-lymphocyte antigen 4 (CTLA-4) gene -1722T/C polymorphism (rs733618) and cancer has been widely assessed, and a definitive conclusion remains elusive." (PMID 24710335, 2014). "Cytotoxic T lymphocyte-associated antigen-4 (CTLA-4) targeted therapy by anti-CTLA-4 monoclonal antibody (mAb) is highly effective in cancer patients." (PMID 25365349, 2014). "After combining all qualified studies, a total of 3420 cancer cases and 3675 controls from 13 eligible case–control studies were included for meta-analysis of the association between the CTLA-4 -1722T/C polymorphism and cancer risk." (PMID 24710335, 2014). "In our meta-analysis, we found significant association between CTLA-4 -1661A/G polymorphism and increased cancer risk in heterozygote model, dominant model and allele model." (PMID 24376736, 2013).